FKBP14 (FKBP prolyl isomerase 14)
Description:
PPIase which accelerates the folding of proteins during protein synthesis. Has a preference for substrates containing 4-hydroxylproline modifications, including type III collagen. May also target type VI and type X collagens.
Synonyms: FKBP22; FLJ20731; EDSKMH; EDSKSCL2; IPBP12
Tractability: Small molecule: it belongs to a druggable protein family. Antibody: UniProt predicts a signal peptide or a membrane-spanning region. PROTAC: ubiquitination databases record sites on it.
Target class: Isomerase; Enzyme
Gene: Protein-coding gene on chromosome 7 (30,010,587 to 30,026,702, reverse strand). Ensembl gene ENSG00000106080.
Subcellular location: Endoplasmic reticulum lumen
Subcellular location (Human Protein Atlas): Cytosol; Golgi apparatus; Nucleoplasm
Pathways (Reactome):
Cellular responses to stimuli: XBP1(S) activates chaperone genes
Gene Ontology:
Molecular function: peptidyl-prolyl cis-trans isomerase activity; protein binding; calcium ion binding
Cellular component: endoplasmic reticulum lumen; endoplasmic reticulum
Genetic constraint (gnomAD): Loss-of-function variants: 17 observed, 18.99 expected, observed/expected ratio (o/e) 0.9, 90% interval 0.61 to 1.34. The upper end of that interval is the gene's LOEUF score, 1.34, which puts it in group 5 of 6, group 1 being the genes least tolerant of losing a copy. Missense variants: 201 observed, 214.02 expected, observed/expected ratio (o/e) 0.94, 90% interval 0.84 to 1.06. Synonymous variants: 63 observed, 75.75 expected, observed/expected ratio (o/e) 0.83, 90% interval 0.68 to 1.03.
Homologues: Orthologues: chimpanzee FKBP14 (100% identical), macaque FKBP14 (99% identical), pig FKBP14 (98% identical), rabbit FKBP14 (94% identical), mouse Fkbp14 (93% identical), guinea pig FKBP14 (91% identical), rat Fkbp14 (75% identical), tropical clawed frog fkbp14 (73% identical), zebrafish fkbp14 (69% identical), Caenorhabditis elegans fkb-5 (20% identical), Caenorhabditis elegans fkb-4 (19% identical). Paralogues in human: FKBP7 (47% identical), FKBP10 (30% identical), FKBP9 (29% identical), FKBP5 (27% identical), FKBP15 (26% identical), FKBP4 (24% identical), FKBP2 (23% identical), FKBP3 (20% identical), FKBP11 (19% identical), FKBP6 (19% identical), FKBP1A (17% identical), FKBP1C (17% identical), and 6 more.
Diseases named in the same sentence as FKBP14 in open-access papers:
FKBP14 is named in the same sentence as 38 diseases in open-access papers, as found by Europe PMC text mining. Sharing a sentence is not in itself a finding about the gene and the disease. The quoted sentences say what the papers report.
Ehlers-Danlos syndrome (5 papers, 2019 to 2025). The Ehlers–Danlos syndromes (EDS) are a clinically and genetically heterogeneous group of heritable connective tissue disorders (HCTDs) characterized by joint hypermobility, skin hyperextensibility, and tissue fragility. "Mutations in the FKBP14 gene encoding FKBP22 (FK506 Binding Protein 22 kDa) cause kyphoscoliotic Ehlers-Danlos Syndrome (kEDS)." (PMID 31949249, 2020).
Kyphoscoliosis (4 papers, 2019 to 2023). An abnormal curvature of the spine in both a coronal (lateral) and sagittal (back-to-front) plane. "The common spinal findings of Larsen syndrome are very similar to the hallmark kyphoscoliosis seen in FKBP14-kEDS." (PMID 37433679, 2023). "We also observed unusually high prevalence of the rs542489955 variant in the FKBP14 gene (MIM#614505; gnomAD NFE AF = 0.001, p = .0061), a frameshift mutation linked to the kyphoscoliosis type of Ehlers‐Danlos syndrome (EDS)." (PMID 31482689, 2019).
hearing loss (3 papers, 2019 to 2021). "FKBP14 gene encodes a protein called FKBP prolyl isomerase 14, and its mutations are linked to hearing loss." (PMID 34454438, 2021). "Diagnostic differentiation criteria:PLOD1-associated kyphoscoliotic type 1 - marfanoid phenotype, profound skin bruisability, scleral and ocular ruptures;FKBP14-associated kyphoscoliotic type 2 - hearing loss, follicular hyperkeratosis, muscular atrophy, bladder diverticulum." (PMID 34504686, 2021). "Hence, we postulate a molecular link between enhanced ALDH1A3 expression and hearing loss in FKBP14-kEDS patients that warrants further investigation." (PMID 31288483, 2019).
osteosarcoma (3 papers, 2021 to 2025). A usually aggressive malignant bone-forming mesenchymal neoplasm, predominantly affecting adolescents and young adults. "FKBP14 is an oncogene that has been reported in several malignant tumors, including osteosarcoma, ovarian cancer, cervical cancer, gastric cancer, and colon cancer." (PMID 34722557, 2021).
breast carcinoma (2 papers, 2021 to 2025). "In conclusion, we identified and constructed a 5-gene signature (GP6, MAK, DCTN2, TMEM156, and FKBP14) prognostic model to predict prognosis in breast cancer patients." (PMID 34722557, 2021). "However, reports on FKBP14 in breast cancer are unavailable." (PMID 34722557, 2021).
cervical cancer (2 papers, 2021 to 2024). A primary or metastatic malignant neoplasm involving the cervix. "Specifically, FKBP14 acts as an oncogene by inhibiting apoptosis and promoting the movement of human cervical cancer." (PMID 34722557, 2021).
colon cancer (2 papers, 2020 to 2021). "FKBP14 promotes the proliferation and migration of colon cancer cells by targeting the IL-6/STAT3 signaling pathway." (PMID 34722557, 2021).
Osteopenia (2 papers, 2019 to 2021). Osteopenia is a term to define bone density that is not normal but also not as low as osteoporosis. "Osteopenia or osteoporosis is a minor criteria in the diagnosis of kEDS, and occurrence of fractures were described in 13% of FKBP14-kEDS." (PMID 31288483, 2019).
aneurysm (1 paper, 2019). Bulging or ballooning in an area of an artery secondary to arterial wall weakening. "We sought to identify DEGs in PLOD1-kEDS and FKBP14-kEDS that are involved in modulating the vasculature, since rupture or aneurysm of medium-sized arteries have been described in both PLOD1-kEDS and FKBP14-kEDS and serves as a minor criteria in the diagnosis of kEDS." (PMID 31288483, 2019).
gastric cancer (1 paper, 2021). A primary or metastatic malignant neoplasm involving the stomach. "The expression of FKBP14 is higher in gastric cancer patients with lower survival rates, and it is associated with lymph node metastasis and advanced histological grade." (PMID 34722557, 2021).
Hernia (1 paper, 2019). "It is noteworthy that 47% of the FKBP14-kEDS patients described developed inguinal or umbilical hernias, a phenotype that is also observed in Efemp1-knockout mice." (PMID 31288483, 2019).
kyphoscoliotic EDS (1 paper, 2023). "In kyphoscoliotic EDS (kEDS; OMIM 225400), deficiency in lysyl hydroxylase (PLOD1) or FKBP22 protein (FKBP14) cause the destabilization of intermolecular collagen crosslinking and folding." (PMID 36756177, 2023).
Larsen syndrome (1 paper, 2023). A rare skeletal dysplasia characterized by congenital dislocation of large joints, foot deformities, cervical spine dysplasia, scoliosis, spatula-shaped distal phalanges and distinctive craniofacial abnormalities, including cleft palate. "In contrast to FKBP14-kEDS, Larsen syndrome is a hereditary connective tissue disorder characterized by congenital dislocations, specifically of the hip, knee, and elbows, with equinovarus or equinovalgus foot deformities." (PMID 37433679, 2023). "Here, we describe a case of FKBP14 kyphoscoliotic Ehlers–Danlos syndrome (FKBP14-kEDS) that was misdiagnosed as Larsen syndrome for 42 years until germline testing was performed during an assessment for hereditary cancer predisposition." (PMID 37433679, 2023).
Sensorineural hearing impairment (1 paper, 2019). A type of hearing impairment in one or both ears related to an abnormal functionality of the cochlear nerve. "Hence, whether diminished PLXNA2 expression has a causal effect on sensorineural hearing impairment in FKBP14-kEDS patients requires further investigation." (PMID 31288483, 2019).
tumor (5 papers, 2021 to 2024). "Among highly perturbed gene pairs across multiple tumor types, we noted CXXC1, HSPA5, GSK3A, SERP1, PDIA6, FKBP14, and SCH1, which showed multiple co‐expression changes." (PMID 34698427, 2021). "Among the genes negatively regulated by KDM4B, STARD7, CPA4, FKBP14, and RNF6 have been shown to regulate cell proliferation and/or metastasis, whereas DYRK2 is a known tumor suppressor." (PMID 34766154, 2021).
connective tissue disorder (4 papers, 2019 to 2024). A disease involving the connective tissue. "Analysis of genes causing connective tissue disorders according to ACGS guidelines revealed four P/LP variants in COL1A1, COL6A1, FKBP14, and ALPL." (PMID 39298385, 2024).
myopathy (1 paper, 2021). A disease of the muscle in which the muscle fibers do not function properly. "EDS caused by mutations in FKBP14 also shows myopathy and progressive kyphoscoliosis." (PMID 34850861, 2021).
FKBP14 also shares sentences with these, for which no sentence is quoted: cancer (2 papers); osteoporosis (2); atherosclerosis (1); Bardet-Biedl syndrome (1); deafness (1); diaphanospondylodysostosis (1); dysautonomia (1); Ehlers-Danlos syndrome, kyphoscoliotic type, 2 (1); Inguinal hernia (1); kyphoscoliosis type of (1); lymph node metastasis (1); muscular atrophy (1); muscular dystrophies (1); ovarian carcinoma (1); ovarian tumor (1); phenylketonuria (1); primary ciliary dyskinesia (1); Pyle disease (1); rectal cancer (1); scoliosis (1); Wilson disease (1).